ABCA12 (ATP binding cassette subfamily A member 12)
Diseases named in the same sentence as ABCA12 in open-access papers (continued):
Sharing a sentence is not in itself a finding about the gene and the disease.
autosomal recessive congenital ichthyosis (14 papers, 2012 to 2026). Autosomal recessive form of inherited ichthyosis. "Research on autosomal recessive congenital ichthyosis (ARCI) with ABCA12 gene mutations has enhanced our understanding of genetic skin disorders." (PMID 39748812, 2024). "Variations in ABCA12 can cause autosomal recessive congenital ichthyosis, marked by abnormal skin scaling and dryness." (PMID 39238930, 2024). "Its expression is regulated by ultraviolet light and loss-of-function mutations in ABCA12 cause the severe skin disorder autosomal recessive congenital ichthyosis (OMIM 607800)." (PMID 24980144, 2014). "Genetic mutations in genes such as CC2D2A, ABCA12, and DOCK6 have been independently implicated in syndromic forms of Joubert syndrome, autosomal recessive congenital ichthyosis (ARCI), and Adams‐Oliver syndrome, respectively." (PMID 41550404, 2026). "Autosomal recessive congenital ichthyosis (ARCI) is associated with mutations in at least 10 genes, such as TGM1, ALOXE3, ALOX12B, ABCA12, and others." (PMID 40565081, 2025). "The genotype-phenotype relationship exhibits a robust correlation in autosomal recessive congenital ichthyosis (ARCI), with the ABCA12 gene frequently implicated in the most severe forms of the disorder." (PMID 39748812, 2024).
lamellar ichthyosis (10 papers, 2015 to 2025). A keratinization disorder characterized by the presence of large scales all over the body without significant erythroderma. "Previous studies connected ABCA12 mutations to ARCI types such as lamellar ichthyosis and congenital ichthyosiform erythroderma." (PMID 39748812, 2024). "The ABC transporter ABCA12 is known to transport glucosylceramide into maturing eLBs, and mutations in ABCA12 result in pathologies like severe lamellar ichthyosis, Harlequin-type ichthyosis, and other diseases, indicating the importance of lipid import during the eLB formation." (PMID 34458262, 2021). "Despite lamellar ichthyosis (LI) being the most prevalent, the heightened severity in this genetic skin disorder spectrum is attributed to homozygous mutations in ABCA12, specifically linked to type 2 LI." (PMID 39371711, 2024).
colorectal cancer (6 papers, 2016 to 2022). A primary or metastatic malignant neoplasm that affects the colon or rectum. "Up-regulation of ABCA12 was found to be associated with anticancer drug resistance in several types of cancer such as breast, ovarian, and colorectal cancer." (PMID 31683902, 2019). "High expression of genes, including ABCA12, was also detected in an army of 151 cancer sufferers (breast cancer, colorectal cancer, and pancreatic cancer)." (PMID 35783291, 2022). "ABCA12 was upregulated in ovarian carcinoma and colorectal cancer, which was recognized as a promising candidate marker." (PMID 33133157, 2020). "When colorectal cancer was compared with the pool of controls and inflammatory bowel disease, the most significant signal in CRC vs controls (upstream of the ABCA12 and ATIC genes) was detected." (PMID 36077729, 2022).
Hyperkeratosis (4 papers, 2012 to 2023). Hyperkeratosis is a histopathological term defining a thickened stratum corneum and may be present in many different skin conditions, with many possible overlaps. "The reported patients’ phenotype with erythema and hyperkeratosis can be associated with the inflammation and hyper-keratinization of the skin due to an impaired epidermal barrier associated with the ABCA12 activity reduction." (PMID 37762265, 2023). "Loss of ABCA12 function in mice causes hyperkeratosis (expanded stratum corneum) and malformed lamellar bodies." (PMID 23226340, 2012). "Since the discovery of ABCA12 as the gene responsible for the HI phenotype, several mouse ABCA12 KO models have been developed and characterized showing good recapitulation of the human HI phenotype: hyperkeratosis, LB malformations, severe barrier dysfunction, and defective lipid homeostasis." (PMID 32544098, 2020). "We have identified a novel mutation in Abca12 that elicits many of the features of HI, including severe hyperkeratosis, LB defects, absence of intercellular lipid lamellae, aberrant protein processing, defective lipid trafficking, limb contractures and the absence of skin barrier function." (PMID 27551807, 2016).
pancreatic cancer (4 papers, 2017 to 2023). "Flow cytometry showed that ABCA12 knockdown reduced the proportion of G0/G1 phase cells and significantly increased the proportion of S phase cells, suggesting that ABCA12 knockdown mainly caused the arrest of pancreatic cancer cell proliferation by inhibiting S phase." (PMID 35783291, 2022). "The results proved that ABCA12 is significantly upregulated in pancreatic cancer cells and that si1-ABCA12 and si3-ABCA12 have the most significant inhibitory effects on ABCA12." (PMID 35783291, 2022). "In this study, we focused on the study of ABCA12 in the pathogenesis of pancreatic cancer and analyzed its carcinogenic mechanism from multiple perspectives through cell line functional phenotypes, clinical tissue data and database information." (PMID 35783291, 2022). "Flow cytometry was used to investigate the effect of ABCA12 on the proliferation cycle and apoptosis of pancreatic cancer." (PMID 35783291, 2022). "In this study, we obtained the gene expression matrix of 182 patients with pancreatic cancer from the TCGA database and confirmed the differential expression of ABCA12 in pancreatic cancer and para-cancer samples." (PMID 35783291, 2022). "Meanwhile, we demonstrated the over-expression of ABCA12 in pancreatic cancer at the cellular level and in clinical tissues for the first time." (PMID 35783291, 2022). "Two different siRNAs and SW1990 cell line were used to construct pancreatic cancer cell models with ABCA12 knockdown." (PMID 35783291, 2022). "Through functional tests, we found that the proliferation and metastasis of pancreatic cancer cells with ABCA12 knockdown were significantly decreased, and the apoptosis level was significantly increased." (PMID 35783291, 2022). "At the same time, the effect of ABCA12 in pancreatic cancer cells was explored at the clinical tissue level and cell lines constructed, and the AKT pathway was confirmed to facilitate the occurrence of pancreatic cancer." (PMID 35783291, 2022). "Notably, ABCA12 knockdown resulted in decreased cell motility, proliferation, and invasion in pancreatic cancer cells, such as SW19952." (PMID 37932340, 2023). "ABCA12 can also affect the biological behavior of pancreatic cancer cells effectively, which may serve as a new target for pancreatic cancer diagnosis and treatment." (PMID 35783291, 2022). "The changes in pathway proteins suggested that ABCA12 may regulate the progression of pancreatic cancer through the AKT pathway." (PMID 35783291, 2022). "Therefore, ABCA12 induces the occurrence and development of pancreatic cancer through the AKT pathway." (PMID 35783291, 2022). "In conclusion, the function of ABCA12 in pancreatic cancer remains to be further revealed." (PMID 35783291, 2022). "Therefore, ABCA12 could promote the proliferation, metastasis and antiapoptosis of pancreatic cancer cells." (PMID 35783291, 2022). "Three genes (ABCA12, B3GNT3, and BMF) and eight miRNA (hsa.miR.577, hsa.miR.503, hsa.miR.3613, hsa.miR.19a, hsa.miR.19b.2, hsa.miR.365a, hsa.miR.365b, and hsa.miR.4668) were found to be dysregulated in four different stages of pancreatic cancer." (PMID 37794108, 2023). "In our study, the western blot assay detected a greater drop in the expression of PAKT in cells after ABCA12 knockdown, while AKT and PI3K remained basically unchanged, confirming that ABCA12 plays an essential part in inducing the occurrence and development of pancreatic cancer via this pathway." (PMID 35783291, 2022).
breast carcinoma (3 papers, 2014 to 2022). "However, higher ABCA12 transcript levels in non-tumor tissues associated with worse response to NACT in breast cancer patients in our previous study." (PMID 33334016, 2020).
melanoma (3 papers, 2014 to 2020). A malignant, usually aggressive tumor composed of atypical, neoplastic melanocytes.
Palmoplantar keratoderma (3 papers, 2016 to 2025). Abnormal thickening of the skin of the palms of the hands and the soles of the feet. "SA‐02, diagnosed with CIE and with the unreported ABCA12 missense mutation p.Arg1514Leu (c.4541G>T), presented a severe skin phenotype, including generalized severe scaling with fine white scales, pronounced erythema and palmoplantar keratoderma." (PMID 30600594, 2019).
Hypertension (2 papers, 2023). The presence of chronic increased pressure in the systemic arterial system. "Furthermore, PIK3C2G, FIBIN, CHRNA1, NPNT, MEOX1, and POU2F2 linked obesity and lung cancer, while PTPRQ, SSUH2, CILP2, CDH2, ABCA12, CPXM1, and L1CAM linked hypertension and lung cancer." (PMID 36685671, 2023).
Alzheimer disease (1 paper, 2012). A progressive, neurodegenerative disease characterized by loss of function and death of nerve cells in several areas of the brain leading to loss of cognitive function such as memory and language. "On the other hand, some ABC transporter family genes such as ABCA1, ABCA2, ABCA7 and ABCA12 are associated with Alzheimer's disease." (PMID 23281790, 2012).
atherosclerosis (1 paper, 2008). A disease characterized by the build-up of fatty material and calcium deposition in the arterial wall resulting in partial or complete occlusion of the arterial lumen. "Our findings suggest that Abca12 is also required for the cholesterol efflux pathway to function and therefore should be taken into account when investigating mechanisms of atherosclerosis or considering targets for its treatment." (PMID 18802465, 2008). "Furthermore, we identify Abca12 as a mediator of Abca1-regulated cellular cholesterol efflux, a finding that may have significant implications for other diseases of lipid metabolism and homeostasis, including atherosclerosis." (PMID 18802465, 2008).
atopic dermatitis (1 paper, 2020). "Although ABCA12 deficiency has not been identified in atopic dermatitis, their association may be deduced from the result showing that ceramides can upregulate ABCA12 expression via the PPAR-mediated signaling pathway." (PMID 32054030, 2020).
bladder cancer (1 paper, 2022). "In addition, differential expression of ABCA12 in metastatic advanced Egyptian bladder cancer has been reported in the tumor field." (PMID 35783291, 2022).
breast tumours (1 paper, 2022). "Nevertheless, the genes ABCA3, ABCA8, ABCA12, ABCC7, and ABCC8 cluster in breast tumours, and the expression of this gene group was associated with the clinical and pathological parameters of tumours." (PMID 35631534, 2022).
ciliopathy (1 paper, 2026). A genetic disorder of the cellular cilia or the cilia anchoring structures, the basal bodies, or of ciliary function. "The phenotype is primarily driven by CC2D2A‐related ciliopathy, with ABCA12, DOCK6 variants, and the 14q31.3–q32.11 deletion acting as likely genetic modifiers." (PMID 41550404, 2026).
colorectal adenocarcinoma (1 paper, 2022). The most common type of colorectal carcinoma. "Some studies screened out some repeatedly mutated genes, including ABCA12, through cancer genome maps and RNA sequencing data as new markers of colorectal adenocarcinoma." (PMID 35783291, 2022).
colorectal adenoma (1 paper, 2022). An adenoma that arises from the colon or rectum. "It has been reported that the expression of ABCA12 is upregulated in CRC, its expression is higher in the colon than in the rectum, and its expression is higher in colorectal adenoma than in hyperplastic polyp." (PMID 36077729, 2022).
COVID-19 (1 paper, 2020). A disease caused by infection with severe acute respiratory syndrome coronavirus 2. "The role of the ATP binding cassette subfamily A member 12 (ABCA12) is not fully elucidated with respect to COVID-19 but assumed to transport lipid via lipid granules to the intracellular space and transporting specific proteases – in the case of harlequin ichtyosis associated with desquamation." (PMID 33293627, 2020).
Joubert syndrome type 9 (1 paper, 2026). "Whole exome sequencing identified a homozygous CC2D2A variant consistent with Joubert syndrome type 9, along with heterozygous variants in ABCA12 and DOCK6, and a 14q31.3–q32.11 deletion." (PMID 41550404, 2026).
keratosis pilaris (1 paper, 2022). A form of dry skin characterized by hair follicles plugged by scale. "ABCA12 gene was reported also in a keratosis pilaris with missense mutation and in Nevus comedonicus with a high protein expression level in the sebaceous gland without any variation in ABCA12 coding region." (PMID 34983512, 2022).
liver cancer (1 paper, 2021). An epithelial or non-epithelial malignant neoplasm that arises from the liver. "Notably in the context of liver cancer, CES2 is associated with drug metabolism, and ABCA12 has been associated with hepatic lipid metabolism." (PMID 34359777, 2021).
osteopetrosis (1 paper, 2021). Osteopetrosis, also known as marble bone disease, is a descriptive term that refers to a group of rare, heritable disorders of the skeleton characterized by increased bone density on radiographs. "At seven loci, there was a single putative causal gene: Abca12 at a locus for adult neurogenesis; Epha4 (stress-coping strategy); Pkn2, Slit3, and Pgk1-rs7 (at three different loci for sleep); H60c (home cage activity); and Adcy1 (osteopetrosis)." (PMID 34311762, 2021).
Palmoplantar hyperkeratosis (1 paper, 2019). Abnormal thickening of the skin localized to the palm of the hand and the sole of the foot. "Furthermore, all Saudi Arabian patients showed palmar hyperlinearity but only TGM1 and ABCA12 affected individuals presented palmoplantar hyperkeratosis, while NIPAL4 and CYP4F22 presented only plantar keratosis." (PMID 30600594, 2019).
pemphigus vulgaris (1 paper, 2021). Pemphigus is a group of chronic autoimmune skin diseases characterized by blister formations on the outer layer of the skin and the mucous membranes. "These important genes include DSG3 and ABCA12 where loss of function results in skin diseases such as pemphigus vulgaris and harlequin ichthyosis." (PMID 33542242, 2021).
peripheral vascular disease (1 paper, 2008). Any disorder affecting blood flow through the veins or arteries outside of the heart. "Cholesterol transport by proteins related to Abca12 plays a critical role in the development of a number of diseases, including heart and peripheral vascular disease, and the description of these functions for Abca12 suggest that it may play a wider role in controlling lipid metabolism." (PMID 18802465, 2008).
rosacea (1 paper, 2023). A chronic erythematous skin disorder that affects the face. "Another interesting study analyzing the skin barrier in rosacea revealed downregulation of the ABCA12 gene, which is responsible for lipid transporter ABCA12, which plays an important role in lipid lamellae formation." (PMID 37108216, 2023).
thyroid cancer (1 paper, 2023). "ABCA8 and ABCA12 are considered hallmark ABC transporters, which may be involved in the regulation of immune cell infiltration in thyroid cancer." (PMID 37563740, 2023).
cancer (9 papers, 2014 to 2025). A tumor composed of atypical neoplastic, often pleomorphic cells that invade other tissues. "Proteins in the ABC family, including ABCA12, have been studied by an increasing number of scientists in the field of cancer, and proteins in this family are expected to become new diagnostic and therapeutic targets in the field of cancer." (PMID 35783291, 2022). "The role of this particular ABCA12 variant in cancer or other diseases is still unknown." (PMID 33334016, 2020). "ABCA12 downregulation impairs cancer stemness and chemoresistance, and its overexpression appears to be associated with metformin resistance in PCa." (PMID 40181576, 2025). "ABCA12 is a highly expressed gene in cancer tissues and cells and has been identified as a key gene related to the prognosis of TNBC for the first time in our study." (PMID 39834541, 2024). "The other altered genes included ABCA12, a transmembrane lipid transporter, required for the proper vesicle trafficking and functioning of secretory granules in cancer cells or ANXA3 which affects the expression of cytokine genes and tumor immune infiltration." (PMID 36604669, 2023). "The expression of ABCA12 in cancer and paracancerous tissues of 30 clinical patients was verified by immunohistochemical experiments." (PMID 35783291, 2022).
tumor (9 papers, 2020 to 2025). "Interestingly, these mutations are present in 3.7% of OSCC patients with up to 27% of tumours losing ABCA12 expression, further proposing the loss of ABCA12 as an initiator of OSCC development." (PMID 34680271, 2021). "At present, ABCA12 is highly expressed in some tumors, but there are few reports on its mechanism of tumor development." (PMID 35783291, 2022). "This suggest that ABCA12 knockdown can assist in the co-promotion of tumor cell apoptosis by therapeutic drugs." (PMID 35783291, 2022). "In this study, the expression of ABCA12 in the tumor database was analyzed by bioinformatics and predicted from multiple perspectives." (PMID 35783291, 2022). "High expression of ABCA12 was closely related to tumor grade and lymphnodes." (PMID 35783291, 2022). "Several upregulated ABC transporters, such as ABCA12, ABCC1 and ABCC4, were also identified, which may contribute to immune-modulatory molecule efflux and further alter the tumor microenvironment." (PMID 39860532, 2025).
genetic skin diseases (3 papers, 2010 to 2022). "HI, the most severe of the three, is an autosomal recessive hereditary skin disorder with very bad prognosis (survival rate is only 56%) caused by mutations in the ABCA12 gene." (PMID 36675662, 2022).
ABCA12 also shares sentences with these, for which no sentence is quoted: congenital ichthyosis (7 papers); congenital ichthyosiform erythroderma (6); skin disorder (6); psoriasis (3); epidermolytic hyperkeratosis (2); Erythema (2); erythrokeratodermia variabilis (2); genetic diseases (2); keratinization disorder (2); lamellar ichthyosis type 2 (2); Netherton syndrome (2); autosomal recessive congenital ichthyosis 4B (1); bacterial infection (1); Cantú syndrome (1); cardiovascular diseases (1); colon cancer (1); dermatitis (1); developmental delay (1); eczema (1); epidermolytic ichthyosis (1); epilepsy (1); gastric cancer (1); harlequin syndrome (1); hepatocellular carcinoma (1); Hyperbilirubinemia (1); hyperplastic polyp (1); ichthyosis vulgaris (1); inflammatory bowel disease (1); Joubert syndrome (1); lung carcinoma (1).
A further 16 diseases each share a sentence with ABCA12 in 1 paper.